ARID1B (AT-rich interaction domain 1B)
Diseases named in the same sentence as ARID1B in open-access papers (continued):
Sharing a sentence is not in itself a finding about the gene and the disease.
Intellectual disability (44 papers, 2012 to 2026). "These challenges are highlighted by our study on clonazepam in ARID1B patients, a common cause of intellectual disability." (PMID 39740803, 2025). "Disease enrichment analysis revealed that these genes are enriched in autism spectrum disorders in patients with ARID1B mutations, while there is a more general enrichment in intellectual disability in patients with SUV420H1 and CDH8 mutations." (PMID 40270680, 2025). "ARID1B is one of the most frequently (~1%) mutated genes with its loss-of-function variants associated with intellectual disability." (PMID 37175659, 2023). "The proband’s clinical manifestations fit the previously reported criteria of disease for CSS or intellectual disability with ARID1B variant." (PMID 35879281, 2022). "Pathogenic variants in ARID1B are one of the top hits (~1%) in large-scale sequencing studies in intellectual disability (ID) populations and ARID1B is also the most frequently mutated gene in Coffin–Siris syndrome (CSS) (OMIM 135900) (51–76%)." (PMID 34440449, 2021). "This was surprising as ARID1B is a common gene mutated in patients with intellectual disability, and learning difficulties are common in children with CSS and ASD." (PMID 33757588, 2021). "We report on a young woman previously diagnosed with intellectual disability due to a de novo mutation in ARID1B, in whom a huge renal and multiple hepatic angiomyolipomas (AMLs) were diagnosed." (PMID 31077186, 2019). "Pathogenic variants in ARID1B are one of the most frequent causes of intellectual disability (ID) as determined by large-scale exome sequencing studies." (PMID 30349098, 2019). "For example, mutations in Arid1b, a gene that is highly expressed in the developing cortical plate and is upregulated in Ts65Dn embryonic forebrain, are implicated in intellectual disabilities in humans." (PMID 29716957, 2018). "Given the associations between Arid1b haploinsufficiency and intellectual disability, we assessed cognitive functions in Arid1b+/- mice." (PMID 28695822, 2017). "By case-control study, retrospective genotype-phenotype analysis and ARID1B gene mutation screening, we found haploinsufficient mutations of ARID1B are associated with syndromic short stature in Coffin-Sirissyndromeor patients with intellectual disability." (PMID 26376624, 2015). "The phenotypes associated with ARID1B haploinsufficiency are variable but common features of the syndromic and nonsyndromic cases include intellectual disability and speech impairment." (PMID 24674232, 2014). "Recent reports have demonstrated that mutations in ARID1B can cause both nonsyndromic intellectual disability and CSS." (PMID 24674232, 2014). "ARID1B is one of the most frequently mutated genes in intellectual disability cohorts." (PMID 39669611, 2024). "Genetic evidence indicates that haploinsufficiency of ARID1B causes intellectual disability (ID) and autism spectrum disorder (ASD), but the neural function of ARID1B is largely unknown." (PMID 33594090, 2021). "ARID1B is one of the most frequently mutated genes in intellectual disability (~1%)." (PMID 34440449, 2021). "Heterozygous variation of ARID1B is a frequent cause of intellectual disability." (PMID 34324492, 2021). "However, ARID1B mutations have also been identified in a broader cohort of patients, including nonsyndromic intellectual disability and deletions in individuals with intellectual disability, autism and agenesis of the corpus callosum." (PMID 24674232, 2014). "Haploinsufficiency of the ARID1B gene is speculated to be a common potential cause of intellectual disability and speech impairment." (PMID 23834954, 2013). "Phenotype–genotype comparison of the translocation patient to seven unpublished patients with various sized deletions encompassing ARID1B confirms that haploinsufficiency of ARID1B is associated with CC abnormalities, intellectual disability, severe speech impairment, and autism." (PMID 21801163, 2012).
Intellectual disability (continued). "ARID1B encodes a DNA binding subunit of the Brahma-associated factor chromatin remodeling complex, which plays a key role in the regulation of gene activity and neurodevelopment, and mutations in this gene have been associated with autism, intellectual disability, and developmental delay." (PMID 27281126, 2016). "Based on this finding, we postulate that while complete loss of the ARID1B gene product causes a syndrome that involves developmental delay, intellectual disability, dysmorphism and short stature, missense mutations may cause isolated short stature without developmental defects." (PMID 26376624, 2015). "ARID1B is not only the most frequently mutated gene in CSS, but also one of the common genes mutated in intellectual disability (ID), with an extremely broad phenotypic spectrum." (PMID 41545737, 2026). "Pathogenic variants in the ARID1B gene on chromosome 6q25 are identified as the leading cause of CSS and are also among the most prevalent causes of intellectual disability." (PMID 40851727, 2025). "Although the exact mechanisms of this gene in AD pathogenesis are unclear, ARID1B mutations have been reported as monogenic causes of autism spectrum disorder (ASD) and intellectual disabilities." (PMID 38702606, 2024). "SSRIDDs have a broad disease spectrum, including NCBRS, CSS, and ARID1B-related nonsyndromic intellectual disability." (PMID 34706719, 2021). "Currently, a clinical trial is ongoing to investigate the effects of clonazepam on children with ARID1B-related intellectual disability in Netherlands (EudraCT: 2019-003558-98)." (PMID 34775996, 2021). "Sequencing studies have implicated haploinsufficiency of ARID1B, a SWI/SNF chromatin-remodeling subunit, in short stature, autism spectrum disorder, intellectual disability, and corpus callosum agenesis." (PMID 28695822, 2017). "ARID1B, which is a member of the SWI/SNF-A chromatin remodeling complex, has been implicated in intellectual disability and autism spectrum disorders." (PMID 26113971, 2015). "Of the genetic defects found outside the MD gene panel, seven genetic defects were found in genes present in the intellectual disability gene panel (ARID1B, SCN1A, ASPM, CTNNB, KDM6A, SMARCA4 and SETBP1)." (PMID 25735936, 2015). "Future studies should investigate if impaired neural development contributes to the intellectual disability and speech impairment that are consistently observed in patients with ARID1B haploinsufficiency." (PMID 24674232, 2014). "We speculate that clonazepam more frequently displays paradoxical effects in patients with ARID1B-related intellectual disability." (PMID 39740803, 2025). "In one study, the phenotype-genotype correlation in seven patients who had various-sized deletions including ARID1B, has shown that haplo-insufficiency of ARID1B is related with intellectual disability, speech impairment, and autism as well as corpus callosum abnormalities." (PMID 32380822, 2021). "Haploinsufficiency of ARID1B has been reported to be recurrently detected in intellectual disability (ID) or mental retardation (MRT), therefore, ARID1B might be the crucial pathogenic factor behind the 6q25 microdeletion syndrome." (PMID 34775996, 2021). "For example, patients with ARID1B-related intellectual disability showed a higher frequency of wakeups in a recent study, and similar differences could be expected in attention deficit hyperactivity disorder, or pediatric asthma." (PMID 33411722, 2021). "For example, BRG1 and BRM mutations (as well as BAF250A/ARID1A and BAF250B/ARID1B mutations) are responsible for Coffin-Siris and Nicolaides-Baraitser syndromes which have similar phenotypic spectrums that include intellectual disability, altered craniofacial features, and distal limb anomalies." (PMID 25544751, 2015).
Intellectual disability (continued). "Another study on intellectual disability analyzed three unrelated patients and revealed three chimeric genes, LIMS1-RANBP2 in patient one, ARID1B-ZDHHC14 in patient two, and ZNF451-KIAA1586 in patient three." (PMID 35627126, 2022). "ARID1B-Related Disorder (ARID1B-RD) is caused by heterozygous pathogenic variants of ARID1B, including classic CSS and intellectual disability with or without nonspecific dysmorphic features." (PMID 38790056, 2024). "ARID1B haploinsufficiency (OMIM #135900, *614556) represents a frequent cause for neurodevelopmental disorders (NDD) comprising nonspecific intellectual disability or Coffin-Siris syndrome." (PMID 31077186, 2019). "Here, we report ARID1B haploinsufficiency in five patients with moderate intellectual disability, absent speech and dysmorphic features with narrow palpebral fissures, long eyelashes, a thin upper lip and full lower lip." (PMID 24674232, 2014). "By contrast, although intellectual disabilities have been reported in ASD patients, the Arid1b hKO exhibited no impairment in learning ability or memory in the Barnes maze, fear conditioning, and T-maze tests (data not shown)." (PMID 28867767, 2017).
developmental delay (21 papers, 2015 to 2025). "The hallmark characteristic that appears to define the Arid1b+/− mice is a developmental delay, as evidenced by an overall total brain volume loss throughout development, and reduced body weight, length, and head width seen as early as PND8." (PMID 33757588, 2021). "However, the formation of fusion led to a small deletion in ARID1B, which may be a cause of developmental delay." (PMID 31007851, 2019). "Almost all ARID1B patients have developmental delay, often with behavioural manifestations such as short attention span and hyperactivity." (PMID 39740803, 2025). "Along with ARID1B, disruption of ADAMTS6 is associated with developmental delay, speech impairment, dysmorphic features and intellectual learning disability." (PMID 36339722, 2022). "Although the combination of laryngomalacia with developmental delay, visual impairment and seizures is suggestive of ARID1B-related ID." (PMID 34440449, 2021). "Patients with a ARID1B duplication have been reported to show moderate developmental delays, hypotonia, and high-arched palate." (PMID 33584783, 2020). "Overall, our study provides a preclinical model for mechanistic and therapeutic dissection of ARID1B related diseases, and offers a translatable avenue to alleviate growth related aspects of developmental delay." (PMID 28695822, 2017). "Given plasma IGF1 deficiency in Arid1b+/- cohorts, we first tested if IGF1 replacement could rescue physical aspects of developmental delay and abnormal behavioral phenotypes." (PMID 28695822, 2017). "We report a boy with developmental delay, feeding difficulties, aspiration, recurrent respiratory infections, slow growth, and hypotonia without a clinical diagnosis, where a previously unreported ARID1B missense variant was classified as a variant of uncertain significance." (PMID 37654076, 2023). "While a few patients with developmental delay have been identified with large deletions in the ADAMTS6 locus, ARID1B is a known regulator of neural development and has previously been associated with intellectual disability." (PMID 36339722, 2022). "ADAMTS6-ARID1B or ARID1B-ADAMTS6 fusion gene formation occurs by translocation in patients with developmental delay; however, no fusion transcripts were formed due to the opposing transcriptional direction in both genes." (PMID 31007851, 2019).
neuroblastoma (18 papers, 2013 to 2025). Neuroblastoma (NB) is the most common solid, extracranial childhood tumor. "ARID1B mutations are known to appear in ~ 10% of neuroblastoma patients and are correlated with poor clinical outcome." (PMID 35660939, 2022). "For example, only 5 out of 72 cases of pediatric neuroblastoma harbor mutations of ARID1B and only 5 out of 26 cases of colorectal cancers harbor mutations of CSMD1." (PMID 30627328, 2018). "They contributed to failures of early stage treatment for NB patients and low survival rate to mutations of the two genes, suggesting ARID1A and ARID1B as contributors to neuroblastoma oncogenesis." (PMID 28055978, 2017). "Although hemizygous deletion in ARID1B was the main type of mutation in neuroblastoma found in the previous study, all ARID1B changes were SNVs and small deletions in the present study." (PMID 28521285, 2017). "ARID1B mutations occur at moderate frequency in neuroblastoma (7%) and HCC (6.7%), with sporadic mutations identified in breast, gastric, and pancreatic cancers too." (PMID 24622842, 2014). "Indeed, deleterious mutations in the genes encoding the mSWI/SNF subunits ARID1A and ARID1B have been reported in neuroblastoma samples and are associated with poor patient prognosis." (PMID 36057593, 2022). "Indeed, proliferative dependency on ARID1B in ARID1A-mutated neuroblastoma cell lines has already been demonstrated in one of these studies." (PMID 36057593, 2022). "In addition, we identified a subgroup of neuroblastoma with ARID1B mutation shows an aggressive behavior." (PMID 28521285, 2017). "However, Sausen and colleagues recently found that ARID1A or ARID1B mutations associate with worse OS in patients with neuroblastoma, and a previous breast cancer study noted that decreased ARID1A expression can confer worse prognosis." (PMID 24622842, 2014). "Interestingly ARID5A was among these 30 de novo mutant genes unique to Met2, and a recent sequencing study has reported that mutations in the chromatin-remodeling genes ARID1A and ARID1B in neuroblastoma were associated with a more aggressive phenotype." (PMID 24147068, 2013). "A proteomic analysis reveals SMARCC1, ARID1A and ARID1B are mainly related to chromatin remodeling in neuroblastoma." (PMID 41142119, 2025). "Structural disruption of the BAF complex, achieved by silencing of its essential subunits and direct SOX11 targets ARID1A and ARID1B, exerted an epigenomic reprogramming in neuroblastoma cells, resulting in reduced neuroblastoma invasiveness and metastasis." (PMID 36882421, 2023). "Mutation of ARID1B is rarer than that of ARID1A in human cancer, but has been found in hepatocellular carcinoma and neuroblastoma." (PMID 29890703, 2018). "The further examination in a large population requires to validate the role of ARID1B mutation on prognosis and possible mutual exclusivity between MYCN and ARID1 in neuroblastoma patients." (PMID 28521285, 2017). "All described aberrations presented below – from chromothripsis to gene deletions, like ATRX, ARID1A and ARID1B genes – have, so far, only been described by sequencing methods of the neuroblastoma genome." (PMID 25161957, 2014). "Chromosomal deletions and sequence alterations in chromatin remodeling genes ARID1A and ARID1B were recently identified in 11% of neuroblastoma cases using massively parallel sequencing techniques." (PMID 24349301, 2013). "Neuroblastoma cells contain three main mSWI/SNF subtypes, but only BRG1-associated factor (BAF) complex disruption through silencing of its key structural subunits, ARID1A and ARID1B, impairs cell proliferation by promoting cell cycle blockade." (PMID 36057593, 2022). "Tumor-specific deletions encompassing ARID1B have been reported in central nervous system tumors, and multiple members of this complex have been identified as tumor suppressor genes in ovarian cancer, pancreatic cancer, liver cancer, and neuroblastoma." (PMID 28521285, 2017).
neuroblastoma (continued). "RNA-Seq of neuroblastoma cells after BAF disruption by silencing of ARID1A and ARID1B with two different shRNAs for each protein revealed the presence of hundreds of transcripts whose expression was modulated after the simultaneous knockdown of both subunits." (PMID 36057593, 2022). "The most frequently harbored alterations of specific genes in neuroblastoma include heritable mutations in the ALK and PHOX2B observed in familial neuroblastoma, chromatin remodeling genes like ATRX, ARID1A and ARID1B and other important genes like PTPN11, MYCN, and NRAS." (PMID 37274289, 2023). "Among the genes not previously known to be involved in neuroblastoma, deletions and sequence alterations of the chromatin-remodeling genes ARID1A and ARID1B were identified in 11% (8 of 71 tumors), and these aberrations correlated with a more aggressive phenotype." (PMID 25161957, 2014).